ZNF804A (zinc finger protein 804A)
Synonyms: C2orf10
Tractability: Antibody: its Gene Ontology location is reachable by antibodies, with high confidence.
Safety:
Unwanted effects reported when the protein is acted on. In parentheses: how it was acted on, where the effect was seen, and who reports it.
opioid dependence (source: ClinPGx)
Gene: Protein-coding gene on chromosome 2 (184,598,529 to 184,939,492, forward strand). Ensembl gene ENSG00000170396.
Subcellular location (Human Protein Atlas): Endoplasmic reticulum
Gene Ontology:
Biological process: positive regulation of gene expression; positive regulation of neuron projection development; regulation of neuron projection development; positive regulation of dendritic spine maintenance
Cellular component: cytoplasm; dendritic microtubule; dendritic shaft; dendritic spine; growth cone; neuronal cell body; nucleus; plasma membrane; postsynapse; axon; presynapse
Genetic constraint (gnomAD): Loss-of-function variants: 2 observed, 17.03 expected, observed/expected ratio (o/e) 0.12, 90% interval 0.047 to 0.37. The upper end of that interval is the gene's LOEUF score, 0.37, which puts it in group 1 of 6, group 1 being the genes least tolerant of losing a copy. Missense variants: 1,470 observed, 1,456.8 expected, observed/expected ratio (o/e) 1.01, 90% interval 0.97 to 1.05. Synonymous variants: 534 observed, 518.75 expected, observed/expected ratio (o/e) 1.03, 90% interval 0.96 to 1.11.
Homologues: Orthologues: chimpanzee ZNF804A (99% identical), macaque ZNF804A (96% identical), pig ZNF804A (80% identical), guinea pig ZNF804A (70% identical), rabbit ZNF804A (70% identical), mouse Zfp804a (67% identical), rat Zfp804a (65% identical), dog ZNF804A (45% identical), tropical clawed frog znf804a (28% identical), zebrafish znf804a (27% identical). Paralogues in human: GPATCH8 (27% identical), ZNF804B (25% identical).
Diseases named in the same sentence as ZNF804A in open-access papers:
ZNF804A is named in the same sentence as 44 diseases in open-access papers, as found by Europe PMC text mining. Sharing a sentence is not in itself a finding about the gene and the disease. The quoted sentences say what the papers report.
schizophrenia (85 papers, 2011 to 2026). A major psychotic disorder characterized by abnormalities in the perception or expression of reality. "ZNF804A was among the first genes robustly associated with schizophrenia based on findings from large-scale genomic studies." (PMID 42160410, 2026). "A single-nucleotide polymorphism in ZNF804A has been associated with combined bipolar disorder and schizophrenia." (PMID 40933952, 2025). "Following the successful initial GWAS screening of schizophrenia‐related alleles, which identified a single locus around the ZNF804A gene, numerous similar studies have been reported." (PMID 40019038, 2025). "Immunochemical analysis revealed that ZNF804a influences the transcriptional activity of four genes associated with schizophrenia and interacts with chromatin near the promoters of two schizophrenia-related genes." (PMID 40933952, 2025). "Both ANK3 and ZNF804A are candidate genes associated with schizophrenia and bipolar disorder based on genome-wide association studies." (PMID 38702695, 2024). "For example, the rs1344706 within the zinc finger protein 804A gene (ZNF804A) has been found a compelling candidate single nucleotide polymorphism (SNP) for schizophrenia." (PMID 35990059, 2022). "For example, an association of a risk allele with better cognitive performance has been observed for another schizophrenia risk gene—ZNF804A." (PMID 36293479, 2022). "We also identified expression changes in key genes previously associated with schizophrenia such as ZNF804A and DRD2, indicating that AS3MT is a key regulator of both these genes." (PMID 35719055, 2022). "As a member of the zinc finger proteins family, ZNF804A has been linked to both schizophrenia and bipolar disorder." (PMID 33833773, 2021). "The gene encoding zinc finger binding protein ZNF804A is a well-recognized schizophrenia risk gene knockdown of which has been shown to decrease TYROBP protein expression in a variant CNS catecholaminergic cell line." (PMID 34321086, 2021). "ZNF804A, a gene that reached the genome-wide significance for schizophrenia and encodes the protein that directly contributes to transcriptional control of schizophrenia associated gene PRSS16 and COMT, raised our interest." (PMID 35046850, 2021). "Genome-wide association studies uncovered the association of ZNF804A (Zinc-finger protein 804A) with schizophrenia (SZ)." (PMID 33303946, 2021). "All four family members were either homozygous or heterozygous for the bipolar risk genotypes in the SYNE1, ANK3, CACNA1C, ODZ4 (TNM4) and ZNF804A genes, of which ZNF804A is also a schizophrenia risk allele." (PMID 32377792, 2020). "The polymorphism rs1344706 in the ZNF804A gene is one of the best-supported risk variants for schizophrenia." (PMID 31193559, 2019). "Association between rs1344706 of ZNF804A and schizophrenia: a meta-analysis Genomics Proteomics Bioinformatics." (PMID 31193559, 2019). "Genome-wide association studies have linked common variation in ZNF804A with an increased risk of schizophrenia." (PMID 30597088, 2019). "Previous studies indicated that single-nucleotide polymorphism (SNP) rs1344706 in ZNF804A was strongly associated with schizophrenia (SCZ)." (PMID 31122238, 2019). "The dataset reports the frequencies of alleles and genotypes of ZNF804A rs1344706 determined in patients with schizophrenia and healthy people from the Russian population." (PMID 31193559, 2019). "•The data on the impact of ZNF804A rs1344706 variants on the severity of symptoms of schizophrenia are important for prediction of disease outcomes." (PMID 31193559, 2019). "CACNA1C and ZNF804A are two genes that have been implicated in schizophrenia and affective disorders through multiple studies, including GWAS and case/control brain expression analyses." (PMID 30142156, 2018). "Variation in the gene encoding zinc finger binding protein 804A (ZNF804A) is associated with schizophrenia and bipolar disorder." (PMID 27837918, 2017).
schizophrenia (continued). "Rs1344706 in the the zinc finger protein 804A (ZNF804A) gene has been identified to be associated with schizophrenia and bipolar disorder (BD) in Europeans." (PMID 28120939, 2017). "Subsequent studies have confirmed association between common variants in ZNF804A and both schizophrenia (SCZ) and bipolar disorder (BP)." (PMID 27837918, 2017). "These included replicated risk variants for schizophrenia associated with imaging phenotypes before, for example, rs11696094 (ZNF804A; ToM, RP), rs2007044 (CACNA1C; EM, RP), rs1702294 (miR137; EM) and rs9636107 (TCF4; EM)." (PMID 28072415, 2017). "In summary, we observed significant association of rs1344706 in the ZNF804A gene with BD and schizophrenia, especially in Northern Chinese populations." (PMID 28120939, 2017). "Recently, rs1344706 in the ZNF804A gene was implicated as one of the most compelling genetic loci that contribute to the susceptibility of both schizophrenia and BD in European populations, supported by the GWAS and follow-up replications." (PMID 28120939, 2017). "A meta-analysis found that putative schizophrenia risk variants in genes including ZNF804A, PRODH, DISC1 and PPP1R1B, reduced functional connectivity, while the genetic changes examined had no overall effect on structural connectivity." (PMID 27450778, 2016). "These transcripts are enriched in immunity-related genes, overlap significantly with those modified by the schizophrenia-associated gene, ZNF804A, and have a reverse expression signature from that seen with antipsychotic drugs." (PMID 27801893, 2016). "Schizophrenia risk polymorphisms of ZNF804A have been also related to differences in performance in the domain of phonology, such as in reading and spelling tasks, but also in the domain of semantics, specifically in task evaluating category fluency." (PMID 27601987, 2016). "ZNF804A was the first gene to achieve genome-wide significance for psychosis, and several studies have confirmed an association between schizophrenia and a single nucleotide polymorphism, rs1344706, in the ZNF804A gene." (PMID 26148198, 2015). "The aim of this study is to use a recall-by-genotype (RBG) design to investigate the biological basis for the association of ZNF804A variants with schizophrenia." (PMID 26498712, 2015). "The rs1344706 single nucleotide polymorphism within ZNF804A was among the first genetic variants found to be associated with schizophrenia." (PMID 26498712, 2015). "A SNP, rs1344706, within ZNF804A was the first to show good evidence for genome-wide association to schizophrenia (p=1.61×10-7), in a sample of 7300 cases and 12,800 controls." (PMID 25315827, 2015). "This circuitry is dysfunctional in patients with schizophrenia, and a polymorphism in ZNF804A associated with risk for schizophrenia is linked with altered hippocampus‐PFC functional connectivity." (PMID 25757652, 2015). "We show that the ZNF804A schizophrenia risk allele is associated with decreased intrahippocampal theta, but increased hippocampal‐PFC coactivation, compared with the nonrisk allele." (PMID 25757652, 2015). "Existing research shows that the rs1344706 variant in ZNF804A is associated with schizophrenia and a range of neuroanatomical and neurocognitive phenotypes." (PMID 26498712, 2015). "Impairments in hippocampus‐PFC functional connectivity are implicated in schizophrenia and are associated with a polymorphism within the ZNF804A gene that shows a genome‐wide significant association with schizophrenia." (PMID 25757652, 2015). "This study has the potential to improve our understanding of both the genetic and neurophysiological basis of sleep and the biological basis for the association of ZNF804A variants with schizophrenia." (PMID 26498712, 2015). "The Box illustrates in more detail some of the key aspects about SNP associations to schizophrenia, taking the example of ZNF804A, arguably the first bona fide schizophrenia risk gene." (PMID 25315827, 2015).
schizophrenia (continued). "SNP rs1344706, in intron two of ZNF804A, was the first variant to reach unequivocal genome-wide significance for schizophrenia, with a later meta-analysis confirming the association and extending it to a broader psychosis phenotype." (PMID 25217366, 2014). "Single nucleotide polymorphisms (SNPs) within the MIR137, TCF4, and ZNF804A genes show genome-wide association to schizophrenia." (PMID 25217366, 2014). "Of note, ZNF804A, a gene implicated in schizophrenia in several studies was experimentally verified although it was not included in the TargetScan putative target list, presumably because of the poor conservation of its binding site." (PMID 23637704, 2013). "One recent GWAS reported association between rs1344706 in ZNF804A and schizophrenia (P = 1.61 × 10-7), and found strong evidence when the affected phenotype included patients with bipolar disorder (P = 9.96 × 10-9)." (PMID 23351715, 2013). "To date, GWASs on schizophrenia have identified several genome-wide significant associated variants located in the zinc finger protein 804A (ZNF804A), neurogranin (NRGN), transcription factor 4 (TCF4) genes and a major histocompatibility complex (MHC) region." (PMID 24160291, 2013). "Evidence from large GWAS indicates that the single nucleotide polymorphism (SNP) rs1344706 in the zinc-finger protein 804A gene (ZNF804A) is associated with psychotic disorders including bipolar disorder and schizophrenia." (PMID 23351715, 2013). "TCF4, like other MHC class I molecule alleles (VRK2 and ZNF804A), were found in genome-wide association studies (GWAS) to be associated with schizophrenia in an Irish population." (PMID 24403877, 2013). "Rs1344706, an intronic SNP within ZNF804A, was identified as one of the most compelling candidate risk SNPs for schizophrenia in Europeans through genome-wide association studies (GWASs) and replications as well as large-scale meta-analyses." (PMID 23776546, 2013). "In the first large genomewide association study of schizophrenia, the common single nucleotide polymorphism (SNP) rs1344706 of the Zinc Finger Protein 804A gene (ZNF804A) was identified as the most significant genetic marker (P< 1.61×10− 7)." (PMID 22840435, 2012). "The first gene to reach genome-wide significance for psychosis was ZNF804a when SNP rs1344706 was significantly associated when schizophrenia and bipolar disorder diagnoses are combined." (PMID 22384243, 2012). "ZNF804A, a genomewide supported susceptibility gene for schizophrenia and bipolar disorder, has been associated with task-independent functional connectivity between the left and right dorsolateral prefrontal cortices." (PMID 22840435, 2012). "Subsequently CACNA1C and ZNF804A were proposed as common risk variants for both bipolar disorder and schizophrenia and a Meta-analysis additionally added the MHC-locus as a common risk factor for both diseases." (PMID 21702894, 2011). "Previous research has implicated ZNF804A in the regulation of gene expression and synaptic function, but the role of this gene in neurodevelopment and in schizophrenia pathogenesis remains unclear." (PMID 42160410, 2026). "Considering that SA deficits in the precuneus are related to ZNF804A rs1344706, a prominent susceptibility gene for schizophrenia, the current results indicate that not only LGI but also SA in the Lt‐MPC is a brain structural characteristic reflecting genetic vulnerability in TRS." (PMID 36165228, 2023). "The hypothesis was partly based on the fact that ZNF804A was shown to be a risk factor not only for schizophrenia but also for bipolar disorder and other psychoses, where cognitive deficits are milder than those in schizophrenia." (PMID 36293479, 2022). "Furthermore, rs1006737 or the CACNA1C and rs1344706 ZNF804A were commonly associated with schizophrenia and bipolar disorder, and recently with brain phenotypes." (PMID 34210021, 2021).
schizophrenia (continued). "Notably, Gpatch8 is the murine ortholog of human zinc finger protein 804A (ZNF804A), a nuclear protein whose dysfunction is linked to schizophrenia." (PMID 34899861, 2021). "We characterized healthy participants according to schizotypy (n = 74) and the single-nucleotide polymorphism rs1344706 in ZNF804A (n = 73), as they represent risk variants for schizophrenia from the perspectives of personality traits and genetics, respectively." (PMID 32059228, 2020). "In addition, a number of sex-specific genetic associations with schizophrenia risk have been reported for several genes such as ZNF804A, the myelin transcription factor 1-like (MYT1L), and interferon γ (IFN-γ)." (PMID 31642026, 2020). "Previous studies indicated that single-nucleotide polymorphism (SNP) rs1344706 in ZNF804A was strongly associated with schizophrenia and might influence social interaction." (PMID 31122238, 2019). "Whether rs1344706 in the ZNF804A gene is associated with schizophrenia therefore remains inconclusive." (PMID 28120939, 2017). "Parenthetically, ZNF804A shows association to schizophrenia in Chinese populations, but to a different SNP, rs1366842; this SNP is coding, and thus may have a different mechanistic basis for its disease association compared with rs1344706." (PMID 25315827, 2015). "ZNF804A (zinc finger protein 804A) illustrates the questions which arise, the approaches which are being taken, and the progress which is being made, when investigating the biological and therapeutic implications of a schizophrenia risk gene." (PMID 25315827, 2015). "A single nucleotide polymorphism in the ZNF804A gene, rs1344706, is associated with schizophrenia." (PMID 26148198, 2015). "These include studies on cortisol and stress neurons derived from hippocampal neurons, DISC1 loss of function in a cortical hNPC model with implication for neuropsychiatric diseases, and knockdown of the schizophrenia and bipolar susceptibility gene, ZNF804a in a cortical hNPC line." (PMID 26296747, 2015). "Previously, many candidate genes, including NRG1 (encoding neuregulin 1), AUTS2 (autism susceptibility candidate 2), TSPAN8 (Tetraspanin-8), ZNF804A (zinc-finger protein 804A), among others, have been identified that might confer risk for schizophrenia." (PMID 26016498, 2015). "Furthermore, zinc finger protein 804A (ZNF804A) is another miR-137 target gene that has been confirmed to be closely associated with schizophrenia." (PMID 24566148, 2014). "ZNF804a was identified by a genome-wide association study (GWAS) in which a single nucleotide polymorphism (SNP rs1344706) in ZNF804a reached genome-wide statistical significance for association with a combined diagnosis of schizophrenia (SZ) and bipolar disorder." (PMID 22384243, 2012). "Moreover, a female-specific association has been observed between ZNF804A and schizophrenia." (PMID 28931092, 2017). "However, unbiased genome-wide analysis of the sequencing data for cryptic structural variation was key to reveal an additional submicroscopic inversion that truncates the schizophrenia- and bipolar disorder-associated brain transcription factor ZNF804A as an equally likely NDD-driving gene." (PMID 24625750, 2014). "One possibility to further clarify this, which in this case was declined by the patient’s family, could be functional MRI, as adult carriers of the common ZNF804A schizophrenia risk allele show reduced cortical thickness and connectivity between and within the dorsolateral prefrontal cortex." (PMID 24625750, 2014). "The zinc finger protein 804A (ZNF804A) and the 5'-nucleotidase cytosolic II (NT5C2) genes are amongst the first schizophrenia susceptibility genes to have been identified in large-scale genome-wide association studies." (PMID 38279611, 2024). "Schizophrenia risk genotype is associated with reduced levels of both NT5C2 and ZNF804A in the developing brain, and a yeast two-hybrid screening suggests that their encoded proteins physically interact." (PMID 38279611, 2024).